LINC00323 (long independently transcribed non-coding RNA 323)
Synonyms: PRED42; FLJ37173; C21orf130; NCRNA00323
Gene: Long non-coding RNA gene on chromosome 21 (41,141,493 to 41,168,796, reverse strand). Ensembl gene ENSG00000226496.
Diseases named in the same sentence as LINC00323 in open-access papers:
LINC00323 is named in the same sentence as 3 diseases in open-access papers, as found by Europe PMC text mining. Sharing a sentence is not in itself a finding about the gene and the disease.
LINC00323 shares sentences with these, for which no sentence is quoted: breast carcinoma (2 papers); gastric cancer (1); osteosarcoma (1).